PCSK9 (proprotein convertase subtilisin/kexin type 9)
Diseases named in the same sentence as PCSK9 in open-access papers (continued):
Sharing a sentence is not in itself a finding about the gene and the disease.
ischemic stroke (continued). "For example, following ischemic stroke induced by transient middle cerebral artery occlusion (tMCAO), PCSK9 expression significantly increased on the lesioned side of the dentate gyrus compared to the non-lesioned side in WT mice." (PMID 32595449, 2020). "Genetic studies in humans report an association between ischemic stroke risk and several GOF mutations in the PCSK9 gene that cause increased plasma LDL-C." (PMID 32595449, 2020). "Rodent studies show upregulation of PCSK9 mRNA levels following transient middle cerebral artery occlusion (tMCAO) to model ischemic stroke." (PMID 32595449, 2020). "Cell lines, animal models, and genetic studies reveal the role of PCSK9 in several CNS diseases including Alzheimer’s disease, alcohol use disorder, ischemic stroke, and neuropsychiatric disorders." (PMID 32595449, 2020). "The available trial data showed PCSK9 inhibitors had a similar effect on MI (OR 0.90, 95% CI 0.86; 0.93) and ischemic stroke (OR 0.85 95% CI 0.78; 0.93)." (PMID 31664920, 2019). "PCSK9 SNPs associated with lower LDL-C predict a substantial reduction in the risk of MI and concordant associations with a reduction in risk of ischemic stroke, but with a modestly increased risk of T2DM." (PMID 31664920, 2019). "The genetic findings presented here show that variation in PCSK9 is associated with lower circulating LDL-C and apoB concentrations, lower risk of MI and, with lesser confidence, the risk of ischemic stroke and coronary revascularization." (PMID 31664920, 2019). "of reperfusion in ischemic stroke, PCSK9 is upregulated in the dentate gyrus of the mouse model but without affecting de novo neurogenesis." (PMID 29770231, 2018). "The overall prevalence of PCSK9 rs505151 and OLR1 rs11053646 variants in ischemic stroke were 0.005 and 0.116, respectively." (PMID 26666837, 2015). "The landmark FOURIER trial showed that PCSK9‐i not only achieve profound LDL‐C reduction (median LDL‐C <25 mg/dL) but also confer robust cardiovascular benefits, including a 15% reduction in cardiovascular mortality and a 21% lower risk of ischemic stroke." (PMID 41190281, 2025). "Mendelian randomization analyses show that people with these PCSK9 loss-of-function alleles have a roughly 25–30% lower risk of ischemic stroke than people without them." (PMID 40863347, 2025). "Over an average follow-up of 2.3 years, PCSK9 inhibitors did not significantly impact cardiovascular mortality but were associated with reduced risks of MI, ischemic stroke, and coronary artery bypass graft compared to control groups." (PMID 39770423, 2024). "Additionally, findings from the FOURIER and ODYSSEY OUTCOMES clinical trials demonstrated a significant reduction in the risk of cerebrovascular disease, encompassing both ischemic stroke and recurrent ischemic stroke, with the utilization of PCSK9 inhibitors." (PMID 39767636, 2024). "Robust evidence from clinical trials suggests that a range of low-density lipoprotein cholesterol (LDL-C)-lowering treatments, such as proprotein convertase subtilisin/kexin type 9 (PCSK9) inhibitors, statins, and ezetimibe, has shown promising efficacy in decreasing the risk of ischemic stroke." (PMID 37881090, 2024). "In conclusion, aside from significantly reducing cholesterol levels, PCSK9 inhibitors may confer beneficial effects on the recurrence of ischemic stroke and cognitive impairment." (PMID 39767636, 2024). "Several clinical trials of PCSK9 inhibitors in patients with ischemic stroke are ongoing, some studies are looking at the effect of PCSK9 inhibitors on acute stroke, and some studies are looking at the effect of PCSK9 inhibitors on intracranial atherosclerotic plaques." (PMID 38273837, 2023).
ischemic stroke (continued). "Therefore, it is necessary to evaluate the efficacy of PCSK9 inhibitors in the acute phase of ischemic stroke in the future." (PMID 38273837, 2023). "Lowering PCSK9 and LDL-C therefore appears beneficial in the context of ischemic stroke but further investigations are needed to test whether PCSK9 inhibition impacts hemorrhagic stroke." (PMID 37586604, 2023). "Thus, our further researches would aim to the in-depth investigation on the molecular mechanism and therapeutic evaluation of PCSK9 inhibition in ischemic stroke model in the future." (PMID 35378805, 2022). "In summary, we generated a GRS predicting PCSK9 function and demonstrated a reduction in risk of several important extra-coronary atherosclerotic phenotypes in addition to known effects on CAD, including PAD, AAA, and ischemic stroke." (PMID 33166319, 2020). "This functional hypothesis has been confirmed by the reduction in CAD and ischemic stroke (IS) reported with PCSK9 inhibition in randomized trials." (PMID 33166319, 2020). "Epigenetic studies reveal that chronic alcohol use may modulate methylation of the PCSK9 gene and genetic studies show that patients with gain-of-function PCSK9 variants have higher LDL-C and an increased risk of ischemic stroke." (PMID 32595449, 2020). "Interestingly, both of the co-dominant models for OLR1 rs11053646 and PCSK9 rs505151 demonstrated similar odds towards ischemic stroke (OR = 1.24, 95% CI:1.02–1.51, p = 0.03; OR = 1.36, 95% CI:1.01–1.85, p < 0.05, respectively)." (PMID 26666837, 2015). "Although it is not statistically significant, the GG genotype carriers of PCSK9 rs505151 had a higher risk of ischemic stroke as compared to the wild-type carriers (OR = 3.56, 95% CI:0.96–13.20, p = 0.06)." (PMID 26666837, 2015). "It is of particular concern that PCSK9 inhibitors can antagonize the enhanced effect of PCSK9 on platelet activity, so it is worth considering whether to use PCSK9 inhibitors directly to alter the prognosis of patients with ischemic stroke with increased platelet activity." (PMID 38273837, 2023). "Moreover, while the application of PCSK9 inhibitors in ischemic stroke primarily pertains to the chronic phase, Alirocumab and Evolocumab have shown the capability to rapidly reduce PCSK9 levels within hours, potentially diminishing the associated risk of ischemic stroke." (PMID 38273837, 2023). "Upon middle cerebral artery occlusion to mimic ischemic stroke, the hyperlipidemic mice exhibited enhanced neuronal apoptosis, cerebral injury, PCSK9, and ApoER2 levels in the brain, which was abrogated by inhibition of PCSK9 using short-hairpin RNA targeting PCSK9 to the cerebral cortex." (PMID 33919550, 2021). "PCSK9‐i demonstrate robust efficacy in reducing LDL‐C levels and mitigating MACEs, particularly ischemic stroke." (PMID 41190281, 2025). "Under the influence of the lack of lipids and PCSK9, atherosclerotic disease is delayed or even improved, and the formation of thrombosis in the body is reduced, which not only dramatically reduces the risk of ischemic stroke but also has important implications for the prognosis of ischemic stroke." (PMID 38273837, 2023). "Therapeutic inhibition of PCSK9 protects against coronary artery disease (CAD) and ischemic stroke (IS)." (PMID 33166319, 2020). "One review revealed that PCSK9 inhibitors plus statins and ezetimibe decreased the incidence of ischemic stroke without increasing the incidence of hemorrhagic stroke." (PMID 37881090, 2024). "While adult neurogenesis occurs in the dentate gyrus, PCSK9 does not appear to play a role in neuronal differentiation after ischemic stroke, as the BrdU cell proliferation assay did not reveal significant de novo neurogenesis in the dentate gyrus." (PMID 32595449, 2020).
ischemic stroke (continued). "PCSK9 mRNA expression was increased in the dentate gyrus but not the infarct or penumbra, suggesting PCSK9 does not play a role in neuronal apoptosis after ischemic stroke." (PMID 32595449, 2020). "Though our understanding of the effects of LDL receptor excess in the brain is still evolving, ablation of the PCSK9 gene in mice did not reveal any significant effect of decreased PCSK9 level on brain recovery after an ischemic stroke." (PMID 29770231, 2018). "Taken together, the current evidences on the role of PCSK9 in the central nervous system suggest that PCSK9 inhibition should not interfere with brain development and morphology or with brain recovery/damage after an ischemic stroke." (PMID 24278757, 2012).
COVID-19 (42 papers, 2020 to 2025). A disease caused by infection with severe acute respiratory syndrome coronavirus 2. "Although not all studies support an association of PCSK9 expression and COVID-19 severity, the subcutaneous injection of evolocumab, a monoclonal inhibitory PCSK9 antibody, in patients with severe COVID-19 lowered the need for intubation and death." (PMID 38388172, 2024). "In this manner, peripheral blood mononuclear cells of COVID-19 patients displayed increased PCSK9 mRNA levels, and a modest association with disease severity was also noticed." (PMID 39408818, 2024). "The findings of this study indicate that elevated serum PCSK9 levels in patients with COVID-19 are only modestly associated with disease severity and serum cholesterol levels." (PMID 39051245, 2024). "This study aims to investigate associations of serum PCSK9, serum cholesteryl ester species, and free cholesterol levels with COVID-19 severity in patients with moderate and severe COVID-19." (PMID 39051245, 2024). "Moreover, this observational study cannot provide information about the underlying processes contributing to higher circulating PCSK9, altered CE profile, and FC levels in COVID-19." (PMID 39051245, 2024). "PCSK9 inhibitors have shown potential antithrombotic effects in preclinical studies, making them a potential avenue to mitigate the increased risk of coagulation disorders and thrombotic events observed in COVID-19." (PMID 38333263, 2024). "We demonstrate the utility of these data for drug discovery by extending the genetic proxied effects of protein targets, such as PCSK9, on additional endpoints, and disentangle specific genes and proteins perturbed at loci associated with COVID-19 susceptibility." (PMID 37794186, 2023). "Uncovering the association between LDL-C and severe COVID-19 is important—proprotein convertase subtilisin/kexin type 9 [PCSK9] inhibitors, a new medication, can significantly decrease LDL-C levels, which might greatly affect prognosis of COVID-19 patients." (PMID 34504873, 2021). "Moreover, PCSK9 inhibitors have shown potential antithrombotic effects in preclinical studies, making them a potential avenue to mitigate the increased risk of coagulation disorders and thrombotic events observed in COVID-19." (PMID 38333263, 2024). "SREBP-2 regulates PCSK9 expression and was also quantified in the liver of patients with COVID-19 and matched controls." (PMID 41233786, 2025). "PCSK9 blockade during the inflammatory phase of SARS-CoV-2 infection reduced disease severity and mortality, indicating a role of high PCSK9 levels in COVID-19 severity." (PMID 41233786, 2025). "Proprotein convertase subtilisin/kexin type 9 (PCSK9) antibodies have also shown potential to protect against COVID-19." (PMID 39408818, 2024). "In a small study, the use of proprotein convertase subtilisin/kexin type 9 inhibitors was shown to increase survival for 30 patients with COVID-19; however, additional larger studies are required to confirm this finding." (PMID 38795859, 2024). "SREBP2 as well as NF-kB, both transcription factors activated upon SARS-CoV-2 infection, can elevate PCSK9 expression and NF-kB or SREBP2 inhibitors normalized PCSK9 levels in PBMCs of COVID-19–infected patients." (PMID 38388172, 2024). "Here, we analyzed PCSK9 in the serum of 55 controls, 40 patients with moderate and 60 patients with severe COVID-19." (PMID 39051245, 2024). "A similar, approximately 2-fold increase in plasma PCSK9 was reported in COVID-19 patients compared to healthy controls." (PMID 39051245, 2024). "While evidence suggests PCSK9’s role in COVID-19 severity, only one study has compared plasma PCSK9 levels between non-infected controls and SARS-CoV-2 infected patients, revealing higher levels in the latter." (PMID 39051245, 2024). "Plasma PCSK9 levels of septic patients due to COVID-19 were significantly higher in contrast to septic patients due to other causes." (PMID 39051245, 2024).
COVID-19 (continued). "Moreover, PCSK9 inhibitors have potential antithrombotic effects in preclinical studies, which may mitigate the increased risk of coagulation disorders and thrombotic events in COVID-19 patients." (PMID 38898389, 2024). "The potential role of proprotein convertase subtilisin/kexin type 9 (PCSK9) inhibition in the management of COVID-19 and other medical conditions has emerged as an intriguing area of research." (PMID 38333263, 2024). "In a study on COVID-19 patients, a single injection of the monoclonal PCSK9 antibody evolocumab led to reduced serum IL-6 levels and improved outcomes compared to placebo at 30 days from baseline." (PMID 39051245, 2024). "PCSK9 serum levels of controls were 0.17 (0.06–0.36) μg/mL, of patients with moderate COVID-19 were 0.37 (0.11–0.72) μg/mL, and of patients with severe COVID-19 were 0.41 (0.20–1.16) μg/mL when patients with liver cirrhosis were excluded." (PMID 39051245, 2024). "The potential role of PCSK9 inhibition in the management of COVID-19 has emerged as an intriguing area of research." (PMID 38898389, 2024). "In the serum of patients with moderate COVID-19, PCSK9 positively correlated with viral load (r = 0.422, p = 0.012)." (PMID 39051245, 2024). "Serum PCSK9 was elevated in moderate COVID-19 compared to controls and further increased in severe cases." (PMID 39051245, 2024). "Clinical trials are needed to establish the efficacy and safety of PCSK9 inhibitors in COVID-19 patients and to determine the optimal timing and dosing for treatment." (PMID 38333263, 2024). "This is an interesting and potentially important finding as there is early evidence that using a PCSK9 inhibitor alters COVID-19 inflammation and outcome." (PMID 38414082, 2024). "PCSK9 blocking antibodies are used to lower serum cholesterol levels and also improve COVID-19 severity and outcome." (PMID 39051245, 2024). "In conclusion, PCSK9 inhibition represents a compelling and multifaceted area of research with potential implications in the management of COVID-19 and other medical conditions." (PMID 38333263, 2024). "Serum PCSK9 was elevated in moderate COVID-19 in comparison to controls and was further increased in severe COVID-19." (PMID 39051245, 2024). "In the context of COVID-19, PCSK9 inhibitors hold promise for their potential to attenuate the cytokine storm, protect against ARDS, and mitigate cardiovascular complications." (PMID 38333263, 2024). "In conclusion, the current study suggests PCSK9 as a possible biomarker for COVID-19, but this needs to be validated in larger cohorts." (PMID 37515197, 2023). "Plasma PCSK9 levels in COVID-19 patients, as well as ARDS patients were about 340 ng/mL, but a comparison with healthy controls was not provided by the authors." (PMID 37515197, 2023). "A substantial variability in plasma PCSK9 levels was observed among the COVID-19 and non-COVID-19 patients." (PMID 37515197, 2023). "In 2019, with the release of the results of phase 3 trials of inclisiran, a PCSK9 siRNA, this field is gaining more attention, even though the paper output is tempered by the outbreak of COVID-19." (PMID 38093957, 2023). "The use of PCSK9 inhibitors for COVID-19 has been considered an opportunity to enhance the antiviral action of interferon in patients with hypercholesterolemia." (PMID 37886946, 2023). "Recent results from a pilot trial testing the ‘Impact of PCSK9 Inhibition on Clinical Outcome in Patients During the Inflammatory Stage of the COVID-19’ (IMPACT-SIRIO 5; NCT04941105) demonstrate a survival benefit among adult patients." (PMID 37365661, 2023). "The exclusion of patients with SIRS from this cohort showed that plasma PCSK9 was still higher in COVID-19 patients." (PMID 37515197, 2023). "Therefore, COVID-19 patients with a gain-of-function mutation of PCSK9 or increased circulating PCSK9 levels (like FH) and type 1 interferon immune deficiency may benefit most from PCSK9 inhibitors." (PMID 38093957, 2023).